TXNDC12 (thioredoxin domain containing 12)
Description:
Protein-disulfide reductase of the endoplasmic reticulum that promotes disulfide bond formation in client proteins through its thiol-disulfide oxidase activity.
Synonyms: ERp18; ERp19; TLP19; hAG-1; AGR1; PDIA16; AG1; ERP16; hTLP19
Tractability: Antibody: UniProt predicts a signal peptide or a membrane-spanning region. PROTAC: ubiquitination databases record sites on it; its protein half-life has been measured.
Gene: Protein-coding gene on chromosome 1 (52,020,130 to 52,055,772, reverse strand). Ensembl gene ENSG00000117862.
Subcellular location: Endoplasmic reticulum lumen
Gene Ontology:
Molecular function: protein binding; protein-disulfide reductase (glutathione) activity; protein-disulfide reductase activity
Biological process: negative regulation of endoplasmic reticulum stress-induced intrinsic apoptotic signaling pathway
Cellular component: endoplasmic reticulum lumen; endoplasmic reticulum
Genetic constraint (gnomAD): Loss-of-function variants: 4 observed, 3.15 expected, observed/expected ratio (o/e) 1.27, 90% interval 0.57 to 1.9. That is too few expected variants to judge how well the gene tolerates losing a copy. Missense variants: 66 observed, 71.84 expected, observed/expected ratio (o/e) 0.92, 90% interval 0.75 to 1.13. Synonymous variants: 18 observed, 30.58 expected, observed/expected ratio (o/e) 0.59, 90% interval 0.41 to 0.87.
Homologues: Orthologues: chimpanzee TXNDC12 (100% identical), pig TXNDC12 (95% identical), guinea pig TXNDC12 (93% identical), rabbit TXNDC12 (93% identical), mouse Txndc12 (90% identical), rat Txndc12 (81% identical), tropical clawed frog txndc12 (74% identical), zebrafish txndc12 (70% identical), Caenorhabditis elegans txdc-12.2 (39% identical), Caenorhabditis elegans txdc-12.1 (38% identical). Paralogues in human: AGR3 (33% identical), AGR2 (32% identical).
Diseases named in the same sentence as TXNDC12 in open-access papers:
TXNDC12 is named in the same sentence as 32 diseases in open-access papers, as found by Europe PMC text mining. Sharing a sentence is not in itself a finding about the gene and the disease. The quoted sentences say what the papers report.
gastric cancer (8 papers, 2015 to 2024). A primary or metastatic malignant neoplasm involving the stomach. "A member of the PDI family, TXNDC12 has been implicated in the tumorigenesis and metastasis of gastric cancer." (PMID 31570854, 2020). "The upregulation of TXNDC12 is observed in certain cancer types, including hepatocellular carcinoma and gastric cancer, where it promotes cell growth, migration, and invasion." (PMID 38047088, 2023). "Immunohistochemical analysis and qRT-PCR of gastric cancer tissues and cell lines showed that TXNDC12 is upregulated in tumors compared to normal tissues." (PMID 35965326, 2022). "TXNDC12 can also promote proliferation, migration, and invasion of gastric cancer cells while TXNDC12 knockdown significantly abolishes these effects." (PMID 35965326, 2022). "TXNDC12 has been demonstrated to contribute to tumorigenicity in human gastric cancer by promoting cell growth, migration and invasion." (PMID 31570854, 2020). "Interestingly overexpression of TXNDC12 significantly enhanced FAK phosphorylation at Tyr-397 and paxillin phosphorylation at Tyr118, suggesting the role of TXNDC12 in the FAK/paxillin pathway in gastric cancer." (PMID 35965326, 2022). "This study was the first study to show that TXNDC12, like other AGR homologues, is involved in tumorigenesis at least in the gastric cancer population while its role in other types of cancer warrants further investigation." (PMID 35965326, 2022). "TXNDC12, as one of the PDI family members, is abnormally expressed in tumours such as gastric cancer and hepatocellular carcinoma, but the role of TXNDC12 in PAAD remains unknown." (PMID 38911386, 2024).
glioma (8 papers, 2020 to 2025). A benign or malignant brain and spinal cord tumor that arises from glial cells (astrocytes, oligodendrocytes, ependymal cells). "TXNDC12 was highly expressed in gliomas and positively associated with immune cell infiltration, playing a vital role in tumor occurrence and progression." (PMID 40034328, 2025). "In glioma studies, TXNDC12 was found to be significantly overexpressed in gliomas, and this high expression was associated with the local immune microenvironment of gliomas, which predicted a poor prognosis for glioma patients." (PMID 38911386, 2024). "We found that TXNDC12 is an independent risk factor for glioma in CGGA-RNA-seq by multivariate analysis (HR = 1.371, 95%CI = 1.188–1.584, p < 0.001)." (PMID 34629960, 2021). "Further regression analysis found that TXNDC12 is an independent risk factor for the prognosis of glioma, which has a certain clinical application value." (PMID 34629960, 2021). "Association of TXNDC12 expression is with the clinicopathological characteristics of patients with glioma." (PMID 34629960, 2021). "Univariate analysis revealed that TXNDC12 is a significant risk factor for glioma in TCGA-RNA-seq (HR = 4.182, 95% CI = 3.185–5.490, p < 0.001) and CGGA-RNA-seq (HR = 2.186, 95%CI = 1.943–2.460, p < 0.001)." (PMID 34629960, 2021). "The expression of TXNDC12 is significantly increased at the mRNA level in gliomas; however, it is unclear whether the expression of the protein encoded by the final target TXNDC12 gene also has corresponding changes." (PMID 34629960, 2021). "Knockdown of TXNDC12 enhances erastin-induced reactive oxygen species, lipid peroxidation and iron accumulation, subsequently reducing glioma cell viability." (PMID 40750708, 2025). "We analyzed the vital role of the TXNDC12 gene in glioma and showed that TXNDC12 is highly expressed in glioma tissue and that it is significantly related to pathological grade and poor prognosis." (PMID 34629960, 2021). "We screened the TXNDC12 gene using public databases and found that it is highly expressed in gliomas, and the expression level increased significantly with the level of gliomas." (PMID 34629960, 2021). "We have demonstrated that high expression of TXNDC12 in glioma predicts adverse outcomes in patients." (PMID 34629960, 2021). "We found that TXNDC12 expression increased significantly as glioma grade increased, both in TCGA (p < 0.01) and CGGA (p < 0.01)." (PMID 34629960, 2021). "The expression of TXNDC12 in the 1p19q codel subgroup increased with glioma WHO grade (p < 0.005) in CGGA." (PMID 34629960, 2021). "To investigate the relationship between TXNDC12 and the local immune microenvironment glioma, we analyzed data from TCGA and CGGA databases." (PMID 34629960, 2021). "The results showed that expression of TXNDC12 (HR = 1.604, 95%CI = 1.178–2.182, p < 0.005) and WHO grade of glioma (HR = 2.059, 95% CI = 1.158–3.662, p < 0.05) were risk factors for glioma patients." (PMID 34629960, 2021). "In samples from TCGA, TXNDC12 expression was significantly higher in glioma tissues compared to normal brain tissues (p < 0.01)." (PMID 34629960, 2021). "Using multicenter and large-sample data, we demonstrated that TXNDC12 is highly expressed in glioma." (PMID 34629960, 2021). "All four genes, P4HB, PDIA4, PDIA5, and TXNDC12, were expressed in glioma cell lines, and these genes were differentially expressed in different cell lines (U251, T98G, A172, U343)." (PMID 32023222, 2020). "In this study, we have shown that the expression of PDIA5 and TXNDC12 was positively correlated with high‐grade gliomas, as well as with wild‐type IDH status and 1p/19q non‐codeletion." (PMID 32301283, 2020). "Furthermore, high expression of TXNDC12 is correlated with poor prognosis in patients with glioma and lung cancers, indicating its potential broader role in cancer development and progression." (PMID 38047088, 2023). "And in glioma, high expression of TXNDC12 predicts the poor prognosis of patients." (PMID 36712973, 2022).
glioma (continued). "GO and KEGG analyses indicated that TXNDC12 may be involved in the malignant prognosis of glioma through glycosylation and antigen processing and presentation." (PMID 34629960, 2021). "Its overexpression closely correlates with glioma prognosis, tumor local immune status, IDH status, and 1p19q status, indicating that TXNDC12 may be a promising prognostic marker for glioma." (PMID 34629960, 2021). "Furthermore, we found that TXNDC12 was an prognostic factor for 3-year and 5-year survival in glioma patients both in TCGA-RNA-seq (AUC3year = 0.787, AUC5year = 0.755) and CGGA-RNA-seq (AUC3year = 0.748, AUC5year = 0.774) by ROC curves." (PMID 34629960, 2021). "We further analyzed the relationship between TXNDC12 expression and glioma pathology grade." (PMID 34629960, 2021). "To further investigate the effect of the difference in TXNDC12 expression among the three subtypes on glioma prognosis, we divided the samples of each subtype into TXNDC12 high-expression and low-expression groups according to the median TXNDC12 expression in the samples." (PMID 34629960, 2021). "The TXNDC12 low expression group of different subtypes had better prognosis, and the combination of these three subtypes can have a better guiding significance for the pathological classification and prognosis judgment of glioma." (PMID 34629960, 2021). "We found that TXNDC12 is involved in the poor prognosis of glioma." (PMID 34629960, 2021). "In addition, TXNDC12 modulates ferroptosis in glioma by regulating SLC7A11 expression." (PMID 40750708, 2025). "However, our assays indicated that erastin- or RSL3-induced iron accumulation in HL60 and K562 cells during ferroptosis was unaffected by the knockdown of TXNDC12, despite a recent study suggesting that TXNDC12 may inhibit iron accumulation in glioma cells." (PMID 38047088, 2023). "Therefore, we speculate that TXNDC12 is likely to confer enhanced proliferation and invasiveness to this type of glioma by increasing the activity of related glycosyltransferases." (PMID 34629960, 2021). "Therefore, we hypothesized that TXNDC12 is involved in the malignant progression of gliomas through the expression of corresponding functional proteins." (PMID 34629960, 2021). "Therefore, we speculate that TXNDC12 may be involved in glioma development and may be used as a potential prognostic molecular marker." (PMID 34629960, 2021). "So, TXNDC12 may serve as a potential molecular marker for glioma pathological grade and prognosis." (PMID 34629960, 2021). "In previous studies, we have proved the significance of TXNDC12 alone, TXNDC12 combined with IDH, and TXNDC12 combined with 1p19q on glioma patient prognosis." (PMID 34629960, 2021). "In the 1p19q Non-codel subgroup, TXNDC12 expression significantly increased with the rise of the grade of gliomas in both TCGA (p < 0.005) and CGGA (p < 0.005)." (PMID 34629960, 2021).
hepatocellular carcinoma (6 papers, 2020 to 2024). A malignant tumor that arises from hepatocytes. "In hepatocellular carcinoma, TXNDC12 promotes EMT and metastasis in tumors." (PMID 36712973, 2022).
breast carcinoma (3 papers, 2003 to 2023). "Data extracted from the Human Protein Atlas showed that YWHAB, SFN, and TXNDC12 expression could distinguish early and late-stage breast cancer in various breast cancer subtypes and are associated with poor patient survival." (PMID 37128318, 2023). "In breast cancer tissue, TXNDC12 mRNA expression is higher compared to normal samples and is significantly correlated with both miRNA clusters in luminal A breast cancer." (PMID 37128318, 2023). "Overall, SFN, YWHAB, TXNDC12, MYL6B, and PRDX4 expressions are significantly associated with breast cancer patient survival." (PMID 37128318, 2023). "TXNDC12, FN1, and PRDX4 have conflicting expressions in breast cancer patient blood compared to control samples in relation to secretory protein expression." (PMID 37128318, 2023). "Therefore, identified upregulated secretory markers YWHAB, SFN, TXNDC12, and MYL6B show strong potential in establishing a battery of breast cancer biomarkers alongside pri-miR526b and pri-miR655." (PMID 37128318, 2023). "While TXNDC12 has not been studied in breast cancer, two gene family members of TXNDC12, ARG2 and ARG3, are known serum-based breast cancer biomarkers." (PMID 37128318, 2023). "Additionally, since both miRNAs and TXNDC12 promote oxidative stress and EMT, TXNDC12 likely collaborates with miRNAs to promote breast cancer cell migration, invasion, and metastasis." (PMID 37128318, 2023). "TXNDC12 expression is not correlated with breast cancer patient survival in non-stratified samples (p = 0.95)." (PMID 37128318, 2023).
glioblastoma (2 papers, 2020 to 2025). The most malignant astrocytic tumor (WHO grade IV). "In addition to in vitro studies, in vivo experiments using stable A172 cells demonstrated a reduction in tumor growth when TXNDC12 expression was modulated, further supporting the idea that inducing oxidative stress through TXNDC12 manipulation can be a viable strategy for treating glioblastoma." (PMID 41009025, 2025).
pancreatic cancer (2 papers, 2024 to 2025). "Then we screened pancreatic cancer-related information through TCGA and GTEx databases and analysed the expression of TXNDC12 in pancreatic cancer, and the results showed that TXNDC12 expression was upregulated in pancreatic cancer tissues." (PMID 38911386, 2024). "Finally, the effect of knocking down TXNDC12 on pancreatic cancer cell functions was able to be reversed by overexpression of GGT7." (PMID 38911386, 2024).
cervical cancer (1 paper, 2022). A primary or metastatic malignant neoplasm involving the cervix. "TXNDC12 was found to have the ability to promote cell migration in cervical cancer cell line and tubule formation in endothelial cells, which can help to give new directions for the treatment of patients with recurrent or refractory cervical cancer in clinic." (PMID 36712973, 2022). "The results showed that TXNDC12 was highly expressed in cervical cancer cell lines." (PMID 36712973, 2022). "Meanwhile, we detected that mRNA of key prognostic genes TXNDC12 and ZC3H13 were highly expressed in cervical cancer cells by RT-qPCR." (PMID 36712973, 2022). "We also analyzed the expression of TXNDC12, CD31 (neovascularization marker gene), and S100A9 (neutrophil marker gene) by IHC experiments in cervical cancer tissues." (PMID 36712973, 2022). "However, even though the literatures point out the role of TXNDC12 or ZC3H13 in tumors, the prognostic impact through angiogenesis and thus involvement in cervical cancer remains unclear." (PMID 36712973, 2022).
leukemia (1 paper, 2023). A malignant (clonal) hematologic disorder, involving hematopoietic stem cells and characterized by the presence of primitive or atypical myeloid or lymphoid cells in the bone marrow and the blood. "To investigate the role of TXNDC12 in ferroptosis, we performed an initial assay to evaluate the expression of TXNDC12 in two human leukemia cell lines (HL60 and K562)." (PMID 38047088, 2023). "We demonstrate that the expression of TXNDC12 is upregulated in human leukemia cells treated with erastin or RSL3, resulting in increased resistance to ferroptosis." (PMID 38047088, 2023). "The inducible expression of TXNDC12 during ferroptosis in leukemia cells is inhibited by the knockdown of the transcription factor ATF4, rather than NFE2L2." (PMID 38047088, 2023). "In summary, TXNDC12 plays a pivotal role in inhibiting lipid peroxidation in leukemia cells in both in vitro and in vivo settings." (PMID 38047088, 2023). "In the present study, we reveal that TXNDC12 exhibits selective upregulation specifically during ferroptosis, while no significant changes are observed during apoptosis in leukemia cells." (PMID 38047088, 2023). "Therefore, the expression of TXNDC12, regulated by ATF4, may function as a negative regulator of lipid peroxidation and subsequent ferroptosis in leukemia cells." (PMID 38047088, 2023).
lung adenocarcinoma (1 paper, 2024). A carcinoma that arises from the lung and is characterized by the presence of malignant glandular epithelial cells. "Although high expression of TXNDC12 can play a role in tumors, a study revealed that low mRNA levels of TXNDC12 can also play a suggestive role in the poor prognosis of lung adenocarcinoma patients." (PMID 38911386, 2024).
oral cancer (1 paper, 2025). "Moreover, we compared the expression patterns of TXNDC12 in normal mouse tongue tissues and tumor tissues from a 4-nitroquinoline 1-oxide-induced oral cancer model." (PMID 40750708, 2025).
oral cavity tumors (1 paper, 2025). "However, stratified analyses within these anatomical subgroups demonstrated that high TXNDC12 expression was significantly associated with worse survival in both nonoral cavity and oral cavity tumors." (PMID 40750708, 2025).
osteosarcoma (1 paper, 2024). A usually aggressive malignant bone-forming mesenchymal neoplasm, predominantly affecting adolescents and young adults. "Among the five DE-ERSRGs, the Kaplan–Meier survival analysis suggested that osteosarcoma patients exhibiting high expression levels of BCL2, MAGEA3, MAP3K5, and TXNDC12 had significantly improved overall survival rates." (PMID 38229155, 2024).